CASP1 (caspase 1)
Diseases named in the same sentence as CASP1 in open-access papers (continued):
Sharing a sentence is not in itself a finding about the gene and the disease.
tumor (continued). "NLRP3/Caspase-1/IL-1β signaling axis within the tumor-infiltrating mononuclear phagocytes promotes tumor growth in GSDMD independent manner in vivo." (PMID 36439171, 2022). "IFNγ can inhibit proliferation of tumor cells and even trigger apoptosis by up-regulating molecules that promote apoptosis, for example, caspase-1." (PMID 36271507, 2022). "Several studies have shown that tumor cells show a decreased caspase-1 expression, and over-expression of caspase-1 can inhibit the growth of tumor cells." (PMID 34773569, 2022). "The cleavage of PPARγ by caspase-1 has been shown to enhance tumor promotion through the induction of TAMs." (PMID 35954274, 2022). "The comparison showed that CASP3 and CASP9 were a higher expression in LGG, and CASP1 staining was consistent in tumor cells and glial cells." (PMID 35964070, 2022). "In tumors, IFN-γ acts as an effective apoptosis-inducing factor by directly inducing caspase-1 and caspase-8 in tumor cells." (PMID 36712869, 2022). "The results showed that the expression of caspase-1 in tumor tissue was significantly higher than that in normal tissue." (PMID 36213831, 2022). "Immunohistochemistry for cleaved Caspase-1 also confirmed comparable numbers and staining intensity for cleaved Caspase-1-positive cells throughout the tumor epithelium of gp130F/F:Nlrp3-/- and gp130F/F mice." (PMID 35299732, 2022). "In the precancerous stage of HPV-infected cells, AIM2 plays a tumor suppressor role by activating caspase-1 to promote pyroptosis of tumor cells." (PMID 36497244, 2022). "During pyroptosis, activated caspase-1 promotes the production of proinflammatory cytokines such as IL-18 an IL-1β7 to regulate the tumor immune microenvironment." (PMID 36384889, 2022). "When we examined the tumor microenvironment in caspase-1 null mice, we found that tumor infiltrating CD45+ cells were significantly reduced in tumors grown in these mice compared to WT mice." (PMID 36439171, 2022). "Increased production of IL-18 and IFN-γ and caspase-1 activation induced by treatment with bLf are important factors contributing to the increase in intestinal mucosal immunity in tumor-bearing mice." (PMID 35264972, 2022). "Our findings demonstrate for the first time that efferocytosis of apoptotic tumor cells activates myeloid-intrinsic NLRP3/caspase-1/IL-1β signaling in the tumor microenvironment." (PMID 36439171, 2022). "Honglin Yan also showed that Cisplatin (DDP) had the effect of an anti-tumor on TNBC, which is brought on by up-regulating MEG3 to cause pyroptosis in NLRP3/caspase-1/GSDMD manner." (PMID 36119049, 2022). "In line with the antagonistic relationship between DNA methylation and gene activation, our DNA methylation analysis revealed a dramatic decrease of CpG methylation levels at promoter regions of Gsdmd, Casp1, and Casp11 in Mll4−/− tumor cells." (PMID 36323669, 2022). "Ech upregulated the expression of NLRP3 and caspase-1 in nude mice NSCLC transplant tumor tissues and inhibited the growth of nude mice NSCLC transplant tumors." (PMID 35571569, 2022). "Activating caspase-1 can either lead to cell death or tumor growth by upregulating the secretion of pro-inflammatory molecules such as IL-1β, IL-18, and FGF2." (PMID 35883451, 2022). "As described by others, we confirmed that the downstream mediator responsible for tumorigenesis was IL-1β as its depletion resulted in significant reduction of tumor growth which phenocopied both the caspase-1 and NLRP3 null mice." (PMID 36439171, 2022). "Studies show that STING (stimulator of interferon genes) agonists can activate NLRP3 by the caspase-1 pathway, thereby promoting the occurrence of pyroptosis and inhibit tumor progression in the Lewis mouse lung cancer model with neoantigen." (PMID 34123855, 2021). "By contrast, caspase 1 can direct T cell-independent tumor proliferation and correlates with a poorer prognosis." (PMID 34867395, 2021).
tumor (continued). "Thereinto, microRNA, approximately 21–23 nucleotides in length, can directly target caspase-1, thereby inhibiting tumor cell proliferation and migration." (PMID 34163438, 2021). "We show that, in the majority of CRCs, tumor cells display an activated and functional caspase-1/IL-18 axis that contributes to drive a Th1/Tc1 response elicited by TILs expressing IL-18Rα." (PMID 33430344, 2021). "Simultaneously, the caspase-1 activity was elevated after the tumour cell cytotoxicity effect, which indicated immunogenic cell death and potential induction of an adaptive anti-tumour immune response." (PMID 34443638, 2021). "In the process of interaction between malignant tumor cells and their microenvironment among them, Caspase-1 actively induces tumor cell programmed death and anti-tumor immune surveillance." (PMID 33741902, 2021). "Treg from non-tumor diseased tissues and tumors shared three upregulated caspase-1 secretomic pathways including extracellular structure, response to reactive oxygen species, cell-substrate junction." (PMID 34084175, 2021). "In lung cancer, caspase-1 inhibition results in the reduction of IL-1β and IL-18, leading to tumour-induced immunosuppression in the lung microenvironment." (PMID 33918087, 2021). "For example, TAM-like cells, generated from THP-1 MΦs cocultured with MCF-7 tumor cells, depend on caspase-1-dependent peroxisome proliferator-activated receptor γ (PPAR γ) cleavage." (PMID 34476174, 2021). "Inhibition of NLRP3 can inactivate caspase-1 and inhibit tumor cell proliferation and migration in many kinds of cancers." (PMID 34239588, 2021). "A semi-quantitative assessment of the percentage of tumor cells with active caspase-1 was performed (scores 0 to 4, see Materials and Methods section)." (PMID 33430344, 2021). "Pyroptosis-related genes (PRGs), such as NLRP3, Caspase 1 (CASP1), Gasdermin D (GSDMD) and Gasdermin E (GSDME), are strongly implicated in oncogenesis and tumor progression." (PMID 34488540, 2021). "For example, VEGFA induces the expression of transcription factor TOX to drive T cell exhaustion, and the expression of CASP1 is able to be repressed by G9A and further promotes tumor immune escape." (PMID 34394098, 2021). "Caspase-1, a key player of pyroptosis, has been shown to act as a tumour suppressor in carcinogenesis." (PMID 33918087, 2021). "In all CRCs, a few macrophages, located in the peritumoral areas and at the tumor invasive front, also expressed active caspase-1." (PMID 33430344, 2021). "Firstly, in the majority of CRCs (70%), tumor cells maintained a functional but aberrantly activated caspase-1/IL-18 axis compared with paired normal colonic epithelial cells." (PMID 33430344, 2021). "In this study, we used two independent cohorts of CRC patients to assess IL-18 expression and caspase-1 activation profiles in tumor cells and studied their relationship with TILs density and microsatellite status." (PMID 33430344, 2021). "A good candidate is the inflammasome pathway that bridges innate and adaptive immunity via the caspase-1/interleukin-18 (IL-18) axis, able to elicit a T-helper/cytotoxic (Th1/Tc1) anti-tumor response." (PMID 33430344, 2021). "Exposure of tumor cells to P.CNF/5-FU resulted in a strong cytotoxic effect, an increased level of caspase-1 released in the culture media and ROS production—the latter directly proportional to the concentration of anti-tumor agent embedded in the scaffolds." (PMID 34452150, 2021). "As an important inflammation-related molecule, Caspase-1 can participate in the regulation of tumor inflammation microenvironment in a variety of ways." (PMID 33741902, 2021). "This study aimed to determine the status of the caspase-1/IL-18 axis in tumor cells and its potential modulatory role on TILs in CRC." (PMID 33430344, 2021).
tumor (continued). "IFNγ levels were the lowest in cluster 3 despite the presence of active caspase-1 in tumor cells and high IL-18 levels." (PMID 33430344, 2021). "Together, our findings showed that the presence of an activated caspase-1/IL-18 axis in tumor cells in the majority of CRCs led to the secretion of mature IL-18." (PMID 33430344, 2021). "In conclusion, this study showed that tumor cells of the majority of CRCs display a functional caspase-1/IL-18 axis, part of the inflammasome pathway, that can modulate the IFNγ response elicited by Th1/Tc1 TILs from the tumor microenvironment." (PMID 33430344, 2021). "We used two independent cohorts of CRC patients to assess IL-18 and caspase-1 expression by tumor cells in relation to the density of TILs and the microsatellite status of CRC." (PMID 33430344, 2021). "Expression of active caspase-1 was observed predominantly in the Epcam+ tumor cells and at a much lower level in the CD11b+ myeloid cells in most of the cases studied." (PMID 33430344, 2021). "Slightly ascending but statistically insignificant profiles of caspase-1 activity suggested the cytotoxic effect of the anti-tumor agent embedded in P.CNF-enriched scaffolds on MCF12A normal breast cells." (PMID 34452150, 2021). "Combination treatment upregulated the expression of GSDME-N and cleaved caspase-1 in tumor tissues, but downregulated the expression of p-EGFR." (PMID 33472170, 2021). "Together, our results strongly suggest that targeting the caspase-1/IL-18 axis can improve the anti-tumor immune response in subgroups of CRC." (PMID 33430344, 2021). "As NLRP3 inflammasome activation usually leads to the autocleavage of caspase-1 and has pro-tumor growth effect in OSCC cells, we further detected the expression of NLRP3." (PMID 35004674, 2021). "The highest levels of caspase-1 were released in the culture medium that we detected in 3D systems composed of tumor cells and scaffolds enriched with 5-FU." (PMID 34452150, 2021). "Noticeably, flow cytometry experiments confirmed that active caspase-1 was present predominantly in Epcam+ tumor cells and in only a few CD11b+ myeloid cells." (PMID 33430344, 2021). "Disruption of inflammasome activation and subsequent caspase-1 activation by thalidomide has shown to suppress tumour growth in relapsed myeloma patients through its anti-angiogenic activity." (PMID 33918087, 2021). "Altogether, our results show that, contrary to the normal colonic mucosa, the majority of CRCs (70%) expressed active caspase-1, predominantly in tumor cells." (PMID 33430344, 2021). "The results were consistent with those in tumor cells, where ERp29 upregulated miR-135a-5p expression and downregulated levels of IL-1β and active form of caspase-1, suggesting that this mechanism is generalized but not cancer specific." (PMID 34667160, 2021). "By contrast, active caspase-1 was detected in tumor cells in 70% (64/96) of CRCs, both MSS and the majority of MSI CRCs (n = 17, i.e., 80% of MSI CRCs)." (PMID 33430344, 2021). "The salient finding of the present study is that cleavage of gC1qR by active caspase-1 promotes aerobic glycolysis in tumor cells and boosts carcinogenesis." (PMID 33102234, 2020). "Taken together, our results support that tumor encounter modifies the TNF/RIPK3-dependent induction of caspase-8 activity to TNF/RIPK3-dependent caspase-1 activity after PH." (PMID 33178579, 2020). "Caspase-1 staining was intense in most stages and types of tumor cells, with punctate stain around nuclei and on some cell surfaces." (PMID 31923221, 2020). "Because an increased expression of NLRP3, ASC, Caspase-1, IL-1β and IL-18 proteins is observed in tumor tissues from Tgfbr1/Pten 2cKO HNSCC mice, there is a rationale for testing the NLRP3 inflammasome inhibitor, MCC950 in this model." (PMID 33261061, 2020).
tumor (continued). "We first assessed the immunofluorescence intensity of selected inflammasome components (NLRP1, NLRP3, NLRP6, AIM2, ASC, Caspase-1, IL-1β and IL-18) in tumor cells compared to normal epithelial cells, for each patient." (PMID 33255437, 2020). "Downstream of RLR family members, expression of NLRP3 inflammasome components are impaired in HCC tumor tissues, i.e., ASC, caspase 1 and IL-1β, which inversely correlated with tumor grade and clinical stage." (PMID 33613561, 2020). "In tumor cells, caspase-1 staining occurred in the cytoplasm, occasional peri-nuclear sites and some punctate cytoplasmic structures." (PMID 31923221, 2020). "In all tumor cell lines and fibroblasts, Caspase 1 inhibition, partially attenuated the effects of LPS/Nigericin." (PMID 33613529, 2020). "When macrophages have consumed dying mammary tumor cells by phagocytosis, AIM2 senses tumor DNA, enabling caspase-1 activation and IL-1β production." (PMID 33261061, 2020). "A recent study of tumor cells showed that induction of caspase-1-mediated pyroptosis by simvastatin in non-small-cell lung cancer (NSCLC) promoted cell death and exerted antitumor effects." (PMID 32303673, 2020). "Caspase-1 inhibition substantially inhibited tumor growth, thus proposing the caspase-1/PPARγ/MCAD pathway as a promising target to prevent TAM-induced tumorigenesis." (PMID 32509781, 2020). "This is further supported by our data on decreased cell death in tumor cells when Caspase 1 was inhibited." (PMID 33613529, 2020). "Future in-vivo investigations will better clarify the efficiency of inflammasome activation and Caspase-1 inhibition on tumor progression." (PMID 33613529, 2020). "Consistent with the in vitro data, these tumor-infiltrating macrophages also showed increased ROS levels, enhanced caspase-1 activity and elevated mature IL-1β production following L-MP treatment." (PMID 31649305, 2020). "In the context of chemotherapy, a study provided evidence that the NLRP3 inflammasome including caspase-1 are important for the induction of tumor-specific IFNγ producing helper CD4+ T cells, since Th1 priming failed in NLRP3 or caspase-1 deficient mice." (PMID 32674488, 2020). "In conclusion, in this study, we, for the first time, analyzed the effect of an inducer (Nigericin) of NLRP3 and inhibitor of Caspase 1 (VX765) in a panel of different tumor types and normal fibroblast controls." (PMID 33613529, 2020). "P63, which is another member of the pathway, was revealed to suppress tumor growth by up-regulating caspase 1 expression." (PMID 33353229, 2020). "Of note, inhibition of the caspase-1/PPARγ/MCAD axis reduced tumor growth in a transgenic mouse model of breast cancer." (PMID 31060333, 2019). "Accordingly, treatment with 5-FU in tumor-bearing mice fed a control diet promoted caspase-1 activation in MDSC (CD11b+ Gr-1+ cells) purified from spleen." (PMID 31217433, 2019). "To investigate this further, we injected anti-CTLA-4 or anti-PD-1 mAb in EG7 tumor-bearing Casp1/11−/− or Nlrp3−/− mice." (PMID 31085177, 2019). "The in vivo study also reproduced our findings in vitro, that is, luteolin suppressed the expressions of AIM2, pro-caspase-1, caspase-1 p10, pro-IL-1β, and IL-1β in tumor samples from nude mice." (PMID 30833546, 2019). "Inflammasomes activate caspase-1, which can act as a tumor suppressor to regulate proliferation and apoptosis." (PMID 31731747, 2019). "2-DG inoculation also attenuated the increased expression levels of NLRP3, caspase-1 p45, and IL-1β p31 in tumor-metastasized lungs." (PMID 30586442, 2018). "The increased tumor incidence found in Nlrp3−/− and Casp1−/− mice correlated with an important local reduction of Il-18 levels and an increased colonic infiltration of macrophages." (PMID 29868004, 2018). "MCC950 inhibited NLRP3 activation and caspase-1 dependent IL-1β processing, and hence improved anti-tumor immune response in head and neck squamous cell carcinoma." (PMID 30631327, 2018).
tumor (continued). "Emerging studies on the expression of inflammasome components ASC and caspase-1 also support the critical role of these molecules in tumor growth and development." (PMID 30631327, 2018). "Increasing evidence suggest that caspase-1-dependent cell death (i.e., pyroptosis) contributes to tumor suppression in various cancers." (PMID 30042341, 2018). "Here, the authors show that stimulation of the innate immunity response with pseudoviruses in a genetic mouse model of intestinal cancer triggers tumour regression via Caspase-1 activation." (PMID 28397782, 2017). "PsV induced pro-caspase-1 processing (p20 fragment) only in tumour tissues that was more pronounced 48 h after immunization." (PMID 28397782, 2017). "We demonstrated that targeting macrophages via caspase-1 specific inhibitors or overexpressing MCAD in macrophages significantly attenuated tumor growth." (PMID 28974683, 2017). "Instead, tumour elimination and prolonged animal survival are mainly achieved via activating the innate ‘inflammasome-caspase-1' pathway." (PMID 28397782, 2017). "We also uncovered the molecular mechanism of how G9A represses CASP1 to promote tumor cell growth and invasion." (PMID 28383547, 2017). "In contrast, caspase-1 KO and WT mice displayed similar tumor growth under normal weight conditions." (PMID 28955343, 2017). "Although it is widely accepted that caspase-1 has an anti-cancer effect, there are some other researches demonstrated that caspase-1 also has the potential to promote tumor invasiveness and metastases." (PMID 28424426, 2017). "Among the multiple inflammatory factors and related proteases, we focused on the expression of caspase-1 on account of its essential role in the formation of tumor inflammatory microenvironments." (PMID 28424426, 2017). "To confirm the role of caspase-1 in promoting tumor growth, we analyzed caspase-1 and truncated PPARγ fragment in TAMs in each group, which validate the phenotype of BMDMs in this experiments." (PMID 28974683, 2017). "By contrast, when CASP1 was knocked down by siRNA in G9A-depleted tumor cells, the invasion and migration capabilities of these cells were rescued." (PMID 28383547, 2017). "In line with this evidence, CASP1 acts as a tumor suppressor regulating proliferation and apoptosis of epithelial cells." (PMID 28388569, 2017). "Treatment of macrophages with caspase-1 inhibitor reduced secreted IL-1β production by a mean of 73% and concomitantly reduced tumour cell adhesion to levels obtained with resting macrophages." (PMID 28551814, 2017). "In the AOM/DSS-induced colorectal cancer model, NLRC4 and caspase-1 KO mice exhibited increased tumor load and tumor number per mice." (PMID 28955343, 2017). "Secretion of IL-1β was caspase-1 dependent, and treatment with caspase-1 inhibitor reduced IL-1β production by 73% and concomitantly reduced tumour cell adhesion to levels obtained with resting macrophages." (PMID 28551814, 2017). "To determine the impact of CASP1 on the CYP1B1 inhibition-mediated anti-tumor effect, we examined the rate of cell proliferation and apoptosis." (PMID 28388569, 2017). "Accordingly, HE staining of lung tissues showed that caspase-1 KO mice with mammary gland tumors had decreased numbers of tumor foci." (PMID 27786298, 2016). "The tumor volume was significantly decreased after treatment with berberine, compared with the control group, and caspase-1 inhibitor attenuated the effects of berberine." (PMID 27705930, 2016). "RT-qPCR analysis of 20 paired tumor and adjacent normal tissue samples revealed that the mRNA levels of ASC, along with IL-1β, CASP1, and NLRP3 in ASC-associated NLRP3 inflammasome were significantly elevated in OSCC tissues." (PMID 27367024, 2016). "Here, we demonstrate for the first time that NLRP3 and its inflammasome-associated proteins, ASC, IL-1β, and CASP1, are highly expressed in OSCC tumor tissues, as examined by immunohistochemistry (IHC), Western blot and RT-qPCR analyses." (PMID 27367024, 2016).